STXBP5L (syntaxin binding protein 5L)
Description:
Plays a role in vesicle trafficking and exocytosis inhibition. In pancreatic beta-cells, inhibits insulin secretion probably by interacting with and regulating STX1A and STX4, key t-SNARE proteins involved in the fusion of insulin granules to the plasma membrane. Also plays a role in neurotransmitter release by inhibiting basal acetylcholine release from axon terminals and by preventing synaptic fatigue upon repetitive stimulation (By similarity). Promotes as well axonal outgrowth.
Synonyms: KIAA1006; LLGL4; tomosyn-2
Tractability: Antibody: UniProt places it where antibodies can reach, with high confidence; its Gene Ontology location is reachable by antibodies, with medium confidence. PROTAC: UniProt records ubiquitination sites on it; its protein half-life has been measured.
Gene: Protein-coding gene on chromosome 3 (120,908,072 to 121,424,761, forward strand). Ensembl gene ENSG00000145087.
Subcellular location: Cytoplasm; Cell membrane; Membrane
Gene Ontology:
Molecular function: protein binding; GTPase activator activity; myosin II binding; syntaxin binding
Biological process: exocytosis; Golgi to plasma membrane transport
Cellular component: cytoplasm; plasma membrane; membrane
Genetic constraint (gnomAD): Loss-of-function variants: 39 observed, 101.01 expected, observed/expected ratio (o/e) 0.39, 90% interval 0.3 to 0.5. The upper end of that interval is the gene's LOEUF score, 0.5, which puts it in group 2 of 6, group 1 being the genes least tolerant of losing a copy. Missense variants: 1,063 observed, 1,194.4 expected, observed/expected ratio (o/e) 0.89, 90% interval 0.85 to 0.94. Synonymous variants: 426 observed, 403.84 expected, observed/expected ratio (o/e) 1.05, 90% interval 0.97 to 1.14.
Homologues: Orthologues: chimpanzee STXBP5L (99% identical), pig STXBP5L (98% identical), rabbit STXBP5L (98% identical), dog STXBP5L (97% identical), rat Stxbp5l (96% identical), mouse Stxbp5l (96% identical), macaque STXBP5L (95% identical), guinea pig STXBP5L (90% identical), tropical clawed frog stxbp5l (81% identical), zebrafish stxbp5l (73% identical), Drosophila melanogaster Tomosyn (44% identical), Caenorhabditis elegans tom-1 (36% identical). Paralogues in human: STXBP5 (66% identical), LLGL2 (25% identical), LLGL1 (25% identical).
Diseases named in the same sentence as STXBP5L in open-access papers:
STXBP5L is named in the same sentence as 12 diseases in open-access papers, as found by Europe PMC text mining. Sharing a sentence is not in itself a finding about the gene and the disease. The quoted sentences say what the papers report.
Cirrhosis (1 paper, 2016). A chronic disorder of the liver in which liver tissue becomes scarred and is partially replaced by regenerative nodules and fibrotic tissue resulting in loss of liver function. "Moreover, a cirrhosis risk score consisting of SNPs in 7 genes (AP3S2, AQP2, AZIN1, DEGS1, STXBP5L, TLR4, and TRPM5) has been shown to predict fibrosis progression in HCV infected patients." (PMID 26950933, 2016).
small cell lung carcinoma (1 paper, 2021). Small cell lung cancer (SCLC) is a highly aggressive malignant neoplasm, accounting for 10-15% of lung cancer cases, characterized byrapid growth, and early metastasis. "Another study confirms that circ-STXBP5L is selectively expressed in small cell lung cancer (SCLC) samples compared with NSCLC." (PMID 33634138, 2021).
type 2 diabetes (1 paper, 2015). "Stxbp5l (also known as tomosyn-2) has been found to play a role in exocytosis regulation of both insulin and acetylcholine, and as such has been nominated as a genetic factor in both type 2 diabetes and neuromuscular disorders." (PMID 26505904, 2015).
tumor (1 paper, 2020). "Four missense variants were heterozygous in the tumor sample and not present in blood (FAM117B, CTNNB1, CELSR3 and STXBP5L)." (PMID 33379206, 2020).
STXBP5L also shares sentences with these, for which no sentence is quoted: diabetes (2 papers); Obesity (2); Alzheimer disease (1); cognitive deficit (1); glioma (1); Hypoglycemia (1); Insulin resistance (1); optic atrophy (1).